UPP1 (uridine phosphorylase 1)
Diseases named in the same sentence as UPP1 in open-access papers (continued):
Sharing a sentence is not in itself a finding about the gene and the disease.
esophageal squamous cell carcinoma (4 papers, 2020 to 2022). Esophageal squamous cell carcinoma (ESCC) is a type of esophageal carcinoma (EC) that can affect any part of the esophagus, but is usually located in the upper or middle third. "Moreover, six abnormally expressed enzymes including pyroline 5-carboxylate reductase 2 (PYCR2) and uridine phosphorylase 1 (Upase 1) that are associated with metabolic pathways were found to be altered in esophageal squamous cell carcinomas." (PMID 34822438, 2021). "This approach revealed, for example, that the functions of pyrroline-5-carboxylate reductase 2 (PYCR2) and uridine phosphorylase 1 (UPP1) are altered in esophageal squamous cell carcinoma." (PMID 33401771, 2021).
Sepsis (4 papers, 2022 to 2024). Sepsis is defined as life-threatening organ dysfunction caused by a dysregulated host response to infection. "The results demonstrated that UPP1 possessed good diagnostic performance (AUC = 0.916) and prognostic prediction performance (AUC = 0.662) for patients with sepsis." (PMID 36982166, 2023). "Next, to explore the ability of UPP1 to diagnose sepsis and predict survival of patients with sepsis, we drew receiver operating characteristic (ROC) curve and calculated area under curve (AUC)." (PMID 36982166, 2023). "Differentially expressed analysis showed that uridine metabolism was indeed dysregulated in sepsis and upregulated UPP1 was also verified in other two GEO datasets." (PMID 36982166, 2023). "It provides a novel insight and rationale for targeting UPP1 by specific inhibitor or uridine supplementation for clinical use to combat sepsis-induced ALI." (PMID 36982166, 2023). "Considering the function of UPP1 proposed to decrease uridine level, we hypothesized that maintaining uridine metabolism homeostasis through uridine supplementation could benefit sepsis-induced ALI." (PMID 36982166, 2023). "To determine which cell may benefit uridine supplementation most, we evaluated the UPP1 expression after LPS stimulation on three cell types, which are representatives for playing a vital role in the pathogenesis of sepsis-induced ALI." (PMID 36982166, 2023). "Consistently, UPP1 was validated to be significantly upregulated in sepsis-induced ALI." (PMID 36982166, 2023). "As expected, UPP1 was significantly upregulated in samples from sepsis compared to healthy." (PMID 36982166, 2023). "Previous studies have found that the expression of UPP1 is increased in the brain of sepsis rats." (PMID 35045818, 2022). "Moreover, we detected the mRNA level of UPP1 in lung tissues of sepsis-induced ALI." (PMID 36982166, 2023). "Interestingly, there were both two differentially expressed uridine metabolism-related genes in GPL339 and GPL1261, and we found that uridine phosphorylase 1 (UPP1) was the only differentially expressed uridine metabolism-related gene in sepsis-induced lung tissue compared to control." (PMID 36982166, 2023). "Thus, UPP1 may affect the occurrence and progression of pediatric sepsis shock by regulating inflammatory and immune responses." (PMID 36439140, 2022). "These suggested that UPP1 may involve in young sepsis patients." (PMID 36439140, 2022). "In the present study, we demonstrated that uridine metabolism is disturbed in sepsis-induced ALI, as manifested by the upregulation of UPP1, which meant to degrade uridine." (PMID 36982166, 2023).
brain glioma (3 papers, 2020 to 2023). A malignant glioma that involves the brain. "In brain glioma, UPP1 was associated with immune and inflammatory response and higher UPP1 levels correlated significantly with a shorter survival time." (PMID 36818562, 2023).
liver fibrosis (3 papers, 2023 to 2025). "A study on liver disease revealed that increasing liver uridine levels through CPBMF 65 (a uridine phosphorylase 1 inhibitor) mitigated CCl4-induced liver fibrosis in mice." (PMID 39933005, 2025). "Our previous work demonstrated a notable reduction in liver uridine levels in a mouse model of S.japonicum-induced liver fibrosis, which was reflected by decreased uridine phosphorylase 1(UPP1) expression." (PMID 40768528, 2025). "Moreover, restraining UPP1 expression to stable uridine homeostasis was reported to prevent progression of liver fibrosis." (PMID 36982166, 2023).
pancreatic ductal adenocarcinoma (3 papers, 2024 to 2025). An infiltrating adenocarcinoma that arises from the epithelial cells of the pancreas. "The flexibility of AMT was further illustrated by its ability to target uridine-dependent pancreatic ductal adenocarcinoma by upregulating uridine phosphorylase 1 (UPP1) in adipose organoids—outcompeting the cancer for its essential metabolic substrate and impeding tumor growth." (PMID 40563875, 2025). "Finally, we show that upregulating UPP1 in adipose organoids can outcompete a uridine-dependent pancreatic ductal adenocarcinoma for uridine and suppress its growth, demonstrating the potential customization of AMT." (PMID 39905264, 2025).
cervical cancer (2 papers, 2021 to 2025). A primary or metastatic malignant neoplasm involving the cervix. "UPP1 has been identified as a predictor of poor survival in cervical cancer, with a strong correlation to common carcinogenesis pathways and inflammation-related pathways." (PMID 39944833, 2025). "Furthermore, we also investigated the therapeutic value of the six‐gene signature and found that it could help predict the response to immune checkpoint inhibitors (ICIs) and that three genes (GLTP, ISG20 and UPP1) in the six‐gene signature might serve as potential drug targets for cervical cancer." (PMID 34498424, 2021).
chronic atrophic gastritis (2 papers, 2022). Atrophic gastritis that is persistent and long-standing. "Recently, UPP1 was reported to play a vital role in immune and inflammatory biological process during particular events such as chronic atrophic gastritis and respiratory allergy." (PMID 35547260, 2022). "Recently, UPP1 also has been reported to play a pivotal role in inflammatory and immune biological processes such as respiratory allergy and chronic atrophic gastritis." (PMID 36439140, 2022).
glioblastoma (2 papers, 2020 to 2022). The most malignant astrocytic tumor (WHO grade IV). "Through analyzing patients’ clinical information and genetic profiles from online databases, TIMP1, ITGA5, FCGR2B, UPP1, ISG20, TSPAN4, and LOXL1 were identified as potential prognostic biomarkers for glioblastoma." (PMID 35778451, 2022). "We found that TIMP1, ITGA5, FCGR2B, UPP1, ISG20, TSPAN4, and LOXL1 are potential biomarkers correlated with the immune infiltration events in patients with glioblastoma." (PMID 35778451, 2022). "In addition, we used the SurvExpress analysis to further assess the prognostic value of TIMP1, ITGA5, FCGR2B, UPP1, ISG20, TSPAN4, and LOXL1 using other glioblastoma patient cohorts, including TCGA Glioblastoma and GSE4412." (PMID 35778451, 2022).
melanoma (2 papers, 2015 to 2023). A malignant, usually aggressive tumor composed of atypical, neoplastic melanocytes. "We have demonstrated that uridine breakdown is promoted by MITF, a transcription factor associated with melanoma progression, which we show binds upstream of UPP1 to promote its expression." (PMID 37198474, 2023). "Accordingly, siRNA-mediated depletion of MITF decreased UPP1 expression in melanoma cells." (PMID 37198474, 2023). "We next investigated the factors that promote UPP1 expression and growth on uridine by integrating our results with CCLE data to prioritize transcription factors, which highlighted MITF as a strong candidate in melanoma cells, both at the protein and the transcript level." (PMID 37198474, 2023).
metastatic cancer (2 papers, 2025). A carcinoma which has spread from the original site of growth to another anatomic site. "Uracil is generated by the enzyme uridine phosphorylase-1 (UPP1), and we find that neutrophils are a significant source of UPP1 in metastatic cancer." (PMID 40702342, 2025). "Mechanistically, our data highlight that neutrophils are a significant source of UPP1 and circulating levels of uracil in metastatic cancer, and demonstrate roles for UPP1 in influencing immune landscapes and ECM deposition in the metastatic lung." (PMID 40702342, 2025). "Given the role of neutrophils in metastasis, and the upregulation of Upp1 in neutrophils from mouse models of metastatic cancer, we sought to understand whether blocking UPP1 activity could influence neutrophil behaviour in the pre-metastatic lung." (PMID 40702342, 2025). "Neutrophils serve as a major source of uridine phosphorylase-1 (UPP1) in metastatic cancer." (PMID 41254689, 2025).
osteoarthritis (2 papers, 2023). A noninflammatory degenerative joint disease occurring chiefly in older persons, characterized by degeneration of the articular cartilage, hypertrophy of bone at the margins and changes in the synovial membrane. "Actually, a similar situation existed in the context of osteoarthritis, in which UPP1 was upregulated and uridine was decreased, and uridine treatment attenuated the severity of osteoarthritis." (PMID 36982166, 2023).
atherosclerosis (1 paper, 2014). A disease characterized by the build-up of fatty material and calcium deposition in the arterial wall resulting in partial or complete occlusion of the arterial lumen. "This is not the case for GBP5, Ubd, SectM1, Ifi16, Upp1 and Fam26F, and could therefore represent potential novel biomarkers of atherosclerosis." (PMID 25478796, 2014).
bladder cancer (1 paper, 2024). "Tissue microarrays provide minimal epidemiological information, which makes it challenging to learn whether bladder cancer patients with specific exposure characteristics are strongly associated with UPP1 expression." (PMID 38385072, 2024). "In addition, we have provided a limited picture of UPP1 protein expression in bladder cancer by tissue microarray, and larger sample sizes are still needed to detect the generalization of UPP1 expression in bladder cancer." (PMID 38385072, 2024). "We believe this may be related to the following reasons: first, we only detected the expression of UPP1 at the mRNA and protein levels in six bladder cancer cell lines, which is a small sample size; second, different expression patterns are widespread in various bladder cancer cell lines." (PMID 38385072, 2024). "However, the effects of UPP1 in bladder cancer (BLCA) have not been elucidated." (PMID 38385072, 2024).
burn (1 paper, 2024). A traumatic injury involving interruption of tissue cohesiveness that results from exposure to caustic chemicals, extreme heat, extreme cold or excessive radiation. "In short, the effect of skin burn on patients is to regulate the expression of immune-related genes UPP1, MMP1, MMP3, and skin regeneration-related gene DPT, which may be the key target for the treatment of skin burn." (PMID 36103997, 2024).
fetal growth restriction (1 paper, 2024). A fetus that does not grow beyond the 10th percentile of conventionally accepted weight for gestational age. "Placental mRNA expression was examined for the 8 genes enriched in isolated trophoblast side-population cells (CXLC8/IL8, ELL2, GATA6, HK2, HLA-DPB1, INTS6, SERPINE3, UPP1) in placentas obtained from participants with early onset preeclampsia (n = 78) or fetal growth restriction (n = 30)." (PMID 39028417, 2024).
gynecologic cancers (1 paper, 2025). "In conclusion, our findings indicate that the expression of 6-CRRGs, including APOBEC3B, HELLS, SLC15A3, CDA, RHOB and UPP1, is associated with the prognosis of patients with common gynecological cancers." (PMID 39944833, 2025). "UPP1 was associated with the pathways of Toll like receptor, Nod like receptor, JAK STAT, chemokine signaling pathways, ECM receptor interaction, focal adhesion, etc., in all these three common gynecologic cancers." (PMID 39944833, 2025).
leukemia (1 paper, 2020). A malignant (clonal) hematologic disorder, involving hematopoietic stem cells and characterized by the presence of primitive or atypical myeloid or lymphoid cells in the bone marrow and the blood. "Therefore, we performed additional in vitro experiments based on the two best 5-protein models (which shared TYMP, RRM1, UPP1, and UCK1 and contained either PPAT or UCK2) using two CRC and two leukemia cell lines that are predicted to be sensitive or resistant to 5FU." (PMID 32686665, 2020).
lymph node metastasis (1 paper, 2019). "That is to say, UPP1 expression serves as a risk of lymph node metastasis." (PMID 31496029, 2019). "Multivariate logistic analysis revealed that UPP1 expression (OR = 3.053, 95% CI 1.957‐4.762, P < .001), clinical stage (OR = 5.117, 95% CI 3.110‐8.419, P < .001) and age (OR = 0.328, 95% CI 0.185‐0.582, P < .001) were associated with lymph node metastasis." (PMID 31496029, 2019). "UPP1 overexpression was significantly correlated with lymph node metastasis, tumour stage and tumour size." (PMID 31496029, 2019). "To examine whether the expression level of UPP1 is correlated with lymph node metastasis, we investigated the connection between them by logistic regression." (PMID 31496029, 2019).
metastatic disease (1 paper, 2025). "Our data indicate that UPP1 can influence neutrophil behaviour, T-cell number and ECM deposition in the lungs of tumour-bearing mice, suggesting that this enzyme can make key contributions to the progression of metastatic disease." (PMID 40702342, 2025).
mitochondrial neurogastrointestinal encephalopathy (1 paper, 2020). "For example, non-human mammals likely possess a UPP1 enzyme with a broader substrate specificity, which may have permitted the loss of the mitochondrial neurogastrointestinal encephalopathy-causing gene TYMP in six mammalian lineages by making it functionally redundant." (PMID 33575564, 2020).
multiple sclerosis (1 paper, 2009). A progressive autoimmune disorder affecting the central nervous system resulting in demyelination. "UPP1 expression has been extensively connected to cancer, stem cells and inflammation such as multiple sclerosis." (PMID 19763259, 2009).
rheumatoid arthritis (1 paper, 2022). A chronic, systemic autoimmune disorder characterized by inflammation in the synovial membranes and articular surfaces. "UPP1 expression was reported to be elevated in synovial fibroblasts in rheumatoid arthritis when compared with cells from individuals not suffering from rheumatoid arthritis specifically in hypoxia." (PMID 35409356, 2022).
Shock (1 paper, 2022). The state in which profound and widespread reduction of effective tissue perfusion leads first to reversible, and then if prolonged, to irreversible cellular injury. "UPP1, S100A9, KIF1B, S100A12, SLC26A8 emerge remarkable diagnostic performance in pediatric septic shock and involved in immune cells infiltration." (PMID 36439140, 2022).
tumor (30 papers, 2003 to 2026). "UPP1 expression also correlated significantly with tumor mutational burden and microsatellite instability (MSI) across multiple cancers and was linked to immune cell infiltration." (PMID 41731765, 2026). "We next conducted a comparative study using both immunocompetent (C57BL/6) and immunodeficient (nude) mice to confirm the association between UPP1 and tumor immunity in vivo." (PMID 38331898, 2024). "To explore the underlying mechanism by which UPP1 modulates PD-L1 expression in tumor cells, we conducted an enrichment analysis on six classical signaling pathways known to regulate PD-L1 in UPP1high tumor cells." (PMID 38331898, 2024). "UPP1 was also more highly expressed in tumorous tissues than in normal tissues, and higher expression of UPP1 was associated with worse survival outcomes." (PMID 36186123, 2022). "Our study established a novel six‐gene (APOC1, GLTP, ISG20, SPP1, SLC24A3 and UPP1) signature that was closely associated with the immune response and the tumour immune microenvironment." (PMID 34498424, 2021). "Our study established a novel six‐gene (APOC1, GLTP, ISG20, SPP1, SLC24A3 and UPP1) signature that was closely associated with the immune response and tumour immune microenvironment." (PMID 34498424, 2021). "UPP1 is mainly involved in tumor‐induced immune response, particularly associated with antigen‐presenting cell‐related immune response and T‐cell activation." (PMID 32583596, 2020). "The up-regulated UPP1 expression increased lymph node metastasis risk and promoted tumor growth." (PMID 33498463, 2021). "Upp1, here reported to be prominently upregulated in cells expressing activated Erk, has recently been reported to be associated with cancer development as an integral component of the metabolic adaptation machinery of the tumor, required for maintaining the transformed phenotype." (PMID 40394416, 2025). "We performed a correlation analysis between the levels of TNF-α and IL-1β expression in macrophages and UPP1 levels in tumor cells." (PMID 41243973, 2025). "Increased neutrophil Upp1 expression was also a feature of splenic neutrophils from tumour-bearing mice, whilst Upp1 was largely undetectable in splenic cells of other lineages." (PMID 40702342, 2025). "Given the positive correlation of uracil with lung metastases, we assessed Upp1 expression in RNA-seq datasets of lung immune cells from tumour-bearing MMTV-PyMT mice (Data Ref:)." (PMID 40702342, 2025). "Owing to the role of UPP1 in uridine usage under glucose-limiting conditions, how UPP1 is regulated and its implications for tumor outcome remain important topics for continued investigations." (PMID 40804482, 2025). "Consistent with our experimental data, the expression of UPP1 in tumor cells is positively correlated with the expression of both cytokines in macrophages." (PMID 41243973, 2025). "Mechanistically, we discovered that macrophages inhibit the pyrimidine salvage pathway in tumor cells by upregulating Upp1-mediated uridine degradation through cytokines TNF-α and IL-1." (PMID 41243973, 2025). "Collectively, these results suggest that the upregulation of Upp1 is essential for promoting phagocytosis in Cad-KO tumor cells." (PMID 41243973, 2025). "Strikingly, however, inhibition of UPP1 with BAU completely opposed the ability of the primary tumour to decrease neutrophil motility in the pre-metastatic lung." (PMID 40702342, 2025). "Expression of Upp1 was also unaltered between cancer cell lines derived from primary tumours grown in the mammary fat pad and cancer cell lines derived from lung micrometastases (Fig. EV1E)." (PMID 40702342, 2025). "Mechanistically, we showed that proinflammatory cytokines released by macrophages, in particular TNF-α and IL-1, synergistically upregulate the expression of UPP1 in tumor cells." (PMID 41243973, 2025).